MIR638 (microRNA 638)
Synonyms: hsa-mir-638; MIRN638
Gene: MicroRNA gene on chromosome 19 (10,718,404 to 10,718,503, forward strand). Ensembl gene ENSG00000207972.
Gene Ontology:
Biological process: miRNA-mediated post-transcriptional gene silencing